IL21 (interleukin 21)
Diseases named in the same sentence as IL21 in open-access papers (continued):
Sharing a sentence is not in itself a finding about the gene and the disease.
infection (continued). "Therefore, infection with Plasmodium spp. drives generation of a large population of IFN-γ+IL-21+ hybrid Th1/Tfh effector cells, which peak in the first week, as well as GC Tfh that are more stably represented, but very few IFN-γ+ Th1-like cells without Tfh markers." (PMID 32634740, 2020). "We asked whether IL-21 supports CD8+ T cell priming in the draining LN following infection." (PMID 27819295, 2016). "Conversely to what has been shown for E75CV1 the progression of the E75-infection resulted in a dramatic imbalance of the immune system by day 7 pi, with the significant up-regulation of 9 genes, namely: IL-5, IL-1β, IL-6, IL-8, IL-10,IL-21, IL-23, DEFB2 and TLR-3." (PMID 26589145, 2015). "Notably, although there is a statistically significant defect in generating germinal center B cells in IL-21R-/- mice, it is much smaller than the defect in establishment of MHV68 infection, indicating that the lack IL-21 signaling has a greater effect on infected B cells than on uninfected B cells." (PMID 25875847, 2015). "HLACs were pretreated with IL-21 and infected with replication competent CCR5-tropic (R5-HIV–green fluorescent protein (GFP)) or CXCR4-tropic (X4-HIV–GFP) HIV-1NL4-3-encoding green fluorescent protein (GFP) to allow for direct quantification of infection by flow cytometry." (PMID 26108174, 2015). "At day 32 post-infection, the numbers of Ter119+ erythrocytic cells in the spleen in the absence of IL-21 signaling were dramatically increased, thus contributing to the large splenomegaly observed in Il21-/- and Il21r-/- mice from day 32 post-infection onwards." (PMID 25763578, 2015). "Importantly, this infection-triggered expansion of the Treg cell population was greatly inhibited by IL-21R signaling in Treg cells, thus defining a novel role for IL-21 in preventing T cell exhaustion and viral persistence via limiting virus-driven Treg cell proliferation." (PMID 23696736, 2013). "Starting from day 14 post-infection (p.i.), six animals were treated with five weekly doses of 50 μg/kg IL-21 (s.c.), which represents a dosage similar or lower to those tested in phase I and II clinical trials in humans (IL-21-treated group; orange in graphs)." (PMID 23853592, 2013). "Finally, in order to assess the extent of the loss of integrity of the epithelial barrier of the GI tract, we performed immunohistochemistry analysis for the polymorphonuclear neutrophil (PMN) infiltration in rectal biopsy tissues of IL-21-treated and control animals at wk6 post-infection." (PMID 23853592, 2013). "Early infection was marked by elevated lung CD4+ T cells (Th17/Treg), diminished Th1 cells and neutrophils, and increased blood cytokines (IFN-γ, IL-21, IL-6, IL-27)." (PMID 42112327, 2026). "Late infection featured further Th1 reduction, neutrophil accumulation, and NETs activation (H3cit, NE-DNA, MPO), along with reduced CXCL9 but elevated IL-6, IL-21, IL-27, CXCL10, and S100A8 in blood." (PMID 42112327, 2026). "HCV antigen–stimulated CD4+ T cells produced IL-21, IFN-γ, and TNF at the week 8 or 11 peak and at lower frequencies at week 20 or 24 after infection." (PMID 40956619, 2025). "infection that the hybrid Th1/Tfh population producing IFN-γ, IL-21, and IL-10 are likely to concurrently provide cellular protection and limit the large humoral response that leads to hypergammaglobulinemia." (PMID 40356908, 2025). "Other cytokines assayed had weak correlation with atRA due to distinctly different cytokine levels in either Asp (IL‐21, IL‐22) or MRSA (TNFα) infection." (PMID 40031928, 2025). "Following secretion of chemokines and cytokines such as IL-1β, IL-6, TNF-α, IL-21, and IL-8, the SARS-CoV-2-induced cytokine storm and hyperinflammatory response have pivotal roles in infection severity, AKI development, and death." (PMID 37026010, 2023). "Decreased production of IL-21 and IL-4 has been reported with human ageing, impairing memory CD4+ T cell responses to infection and vaccination efficacy." (PMID 37106796, 2023).
infection (continued). "CD4+ T cells are crucial in the whole-body resistance to HAV infection, and they produce a large number of cytokines in the early stages of infection, including IFN-γ, TNF-α, IL-2, and IL-21." (PMID 36248427, 2022). "In order to determine the contribution of pre-existing plasma cells to the IL-21 effect, when we performed similar experiments where CD138+ plasma cells were loaded with tracking dye to monitor their survival and response to infection and IL-21 stimulation." (PMID 36569889, 2022). "Thus, whether the altered IL-10 or IL-21 expression at later or chronic stages of infection influences the likelihood of memory populations to adopt the phenotype of atypical B cells or Tr1 cells, and whether this impacts functional memory, remain priority questions." (PMID 35631044, 2022). "We show that IL-21 signaling promotes KSHV infection by promoting both total plasma cell numbers and increasing KSHV infection in plasma cells as early as 3 days post-infection." (PMID 36569889, 2022). "Our current analysis demonstrates IL-21+ CD8+ central memory T cells at both baseline and 3dpi are correlated to the frequency and infection of plasma cells." (PMID 36569889, 2022). "Both IL-21 and IL-6 are important for generating Tfh CD4+ T cells that are selected for during LCMV Cl 13 infection." (PMID 34696381, 2021). "In a separate study, IL-21 secretion by CD4+ T cells was noted to support CD8+ cytotoxic T cell responses in chronic progressors, even during the late-stage infection, leading to diminished virus replication." (PMID 34721397, 2021). "Surprisingly, given that IL-21 is paradigmatically mainly produced by CD4+ cells, we have found IL-21 expression in B cells during the experimental infection." (PMID 35071041, 2021). "The PLS showed that the levels of GMCSF, Fractalkine, IFNg, ITAC, IL-1ß, IL-2, IL-5, IL-7, IL-8, IL-10, IL-12, IL-17α, IL-21, IL-23, MIP-1ß, and TNFα had higher impact on the separation between the uninfected and the pre-infection cohort." (PMID 33731158, 2021). "The percentages of IL-4+, IL-5+, IL-6+, IL-21+, IL-1α+, and IL-17+ γδT cells were increased (p < 0.05), but the percentage of IFN-γ-expressing γδT cells decreased (p < 0.05) post-infection." (PMID 33588839, 2021). "In both infections, STAT3 TKO mice also had a significant reduction in IFN-γ-IL-21+ Teff, supporting reports that STAT3 signaling promotes IL-21 expression." (PMID 32634740, 2020). "In the first week of infection, the majority of Teff produce both IFN-γ and IL-21, averaging 41.67% of Teff in P. chabaudi and 48.57% in P. yoelii in the first week of infection." (PMID 32634740, 2020). "The expression of cytokines involved in B cell survival/maturation, IL-10, IL-21 and BAFF were measured in LN MΦ upon FL13 infection." (PMID 31130951, 2019). "Results show that infection induced Tfh cells has significantly improved the ability to produce IL-21, IL-17, and IFN-γ, especially IL-21, compared with control Tfh cells (P < 0.05)." (PMID 31572373, 2019). "Unlike previous studies with Helicobacter pylori where infection causes adenocarcinoma and produces high levels of IL-17 and IL-21, only moderate increase in signature cytokines secreted by Th17 cells, such as IL-17, IL-17F, IL-21, and IL-22, was observed in our experiments." (PMID 29445365, 2018). "In contrast, the initial HAM response to infection displays a lag phase with few genes significantly up-regulated at the 2 h post-infection time point (CSF2, IL-1B, IL-6, IL-10, IL-21)." (PMID 29847580, 2018). "Additionally, IL-21 could promote infection via M2 polarization of macrophages." (PMID 28103263, 2017). "Their dysfunction reduces IL-21 production in the infected host, which compromises CD8 T cell immunity leading to increased reactivation of the infection." (PMID 29163509, 2017).
infection (continued). "Following infection, expression levels of the immunomodulatory cytokines C-C motif chemokine 22 (CCL22), CCL1, IL-23α, IL-3, IL-4, matrix metalloproteinase 9 (MMP9), IL-21, C-X-C motif chemokine 2 (CXCL2), and CCL2 were increased." (PMID 28507072, 2017). "In the present study, we demonstrate that Tfh are a critical CD4 T cell subset, which expand in response to T. gondii challenge and are an important source of IL-21, the cytokine that regulates CD8 exhaustion during the chronic phase of infection." (PMID 29163509, 2017). "We have analyzed transduction efficiencies (multiplicity of infection (m.o.i.)= 1) following stimulation of naïve T cells for 48 h with magnetic anti-CD3/CD28 beads and IL-7, IL-15 and IL-21." (PMID 27435312, 2016). "In accordance with their results, we demonstrated that IL-21 produced by Tfh cells was correlated to serum IgG level, which implied an important role in regulating humoral immune response against HPV-6/11 infection in JORRP patients." (PMID 27821867, 2016). "The majority of IL-21-producing CD4+ T cells in the spleens of WT C57BL/6 mice co-expressed IFN-γ; in particular at the peak of infection, when over 70% of the IL-21-producing CD4+ T cells in the spleen also expressed IFN-γ." (PMID 25763578, 2015). "iNKT cells are early producers of IFN-γ in HSV-2 infection and can also secrete large quantities of IL-21 that can trigger NK cell and CTL function, reduce infection severity and improve host survival." (PMID 26161082, 2015). "Here we show that interleukin 21 (IL-21), one of the signaling factors produced by CD4 T cells, is required for efficient establishment of infection in a mouse model of gammaherpesvirus infection." (PMID 25875847, 2015). "To delineate the role of IL-21 signaling in MHV68 infection, we characterized infection in IL-21R-/- mice." (PMID 25875847, 2015). "Consistent with the role of STAT3 in IL-21-mediated IL-1β expression, Il1b mRNA was also lower in lungs from Stat3−/− than from WT mice after PVM infection." (PMID 26269257, 2015). "P. chabaudi-infected Il21-/- and Il21r-/- mice showed significantly greater spleen cellularity compared with WT C57BL/6 controls as early as 32 days post-infection, and dramatic splenomegaly at later time points." (PMID 25763578, 2015). "Intrinsic differences in the antigens and co-stimulations delivered by different infections or immunizations could then differentially engage signals able to compensate different aspects of the B-cell response that would otherwise require signaling through IL-21." (PMID 25763578, 2015). "The total number of CD4+ T cells co-expressing IL-21 and IFN-γ showed a dramatic increase by day 8 post-infection, remained high at day 15 post-infection, and decreased thereafter." (PMID 25763578, 2015). "The highest number of IL-21-producing CD4+ T cells co-expressing IFN-γ and IL-10 was detected at day 15 post-infection." (PMID 25763578, 2015). "Furthermore, they suggest that besides its primary function as a direct survival signal for antiviral CD8+ T cells during chronic infections, IL-21 may also indirectly promote CD8+ T cell poly-functionality by restricting the suppressive activity of infection-induced Treg cells." (PMID 23696736, 2013). "To further demonstrate the roles of RagB- and mGITRL-contained plasmid in anti-infection by challenging with P. gingivalis, we analyzed mRNA levels of IFN-γ and IL-21 in spleen cells of mice by real time RT-PCR, and their protein levels by ELISA." (PMID 23560053, 2013). "Both Il2 (GFP) and Il21 (mCherry) were predominantly expressed by CD4+ compared to CD8+ T cells and frequencies increased from days 7–15 post infection with low dose LCMV-WE." (PMID 23696736, 2013). "those that are highly upregulated only by infection with virulent S. flexneri (CCL4, CCL20, IFN-γ, IL-1β, IL-4, IL-6, IL-8, IL-12/23p40, IL-21, TNF-α, CAP-18, LeukoP and COX-2); ii." (PMID 22675469, 2012).
infection (continued). "Meanwhile, both the inducing cytokines (TGF-β, IL-6, IL-23 and IL-21) and the inhibitory cytokines (IFN-γ and IL-4) of Th17 cell generation all increased after infection." (PMID 22102924, 2011). "Together, these in vitro results indicate that infection with ΔEBNA2 EBV is sufficient to confer long-term proliferation potential to primary cord blood B cells on the IL21/CD40L expressing feeder layer even in the absence of any cooperating oncogenes." (PMID 38620028, 2024). "IL-21 treatment also strongly down-modulated EBNA2 target gene CD23 abundance when applied at multiple distinct timepoints between days 2 and 35 post-infection." (PMID 38683861, 2024). "We assessed therefore whether an ELISpot IL-21 assay on CD4+T cells, conducted simultaneously at the same time as serology on samples obtained closest to the time of breakthrough infection, could predict the humoral response." (PMID 39104410, 2024). "Nur77-GFPHI cells did express more Il21 than Nur77-GFPLO cells, consistent with the requirement of this cytokine for optimal protection in the mouse model of TB23 and suggesting an important role for IL-21 signaling at the site of infection." (PMID 38110410, 2023). "Although it is not possible to define the role of the Vδ2+γδ-T cell subset in mice due to the absence of the Vδ2 chain in mice, in general γδ-T cells produce IL-21 and IFN-γ that may enhance humoral immune response against blood stage infection." (PMID 36146602, 2022). "Thus, it is possible that, in combination with other immunological factors, IL-21 may influence KSHV infection at physiological levels in samples where specific milieus including IL-21 producing T cells provide an advantageous environment for the establishment of infection." (PMID 36569889, 2022). "We investigated the role of IL-21, a CD4+ T follicular helper cell (Tfh) regulator, on flu vaccine antibody response in nonhuman primates (NHPs) in the context of age and controlled SIV mac239 infection." (PMID 34491910, 2021). "Furthermore, IL-6 stimulates the production of IL-21 by CD4 T cells and exerts a pro-survival role that can impact the effector/memory population in the context of infection." (PMID 34234771, 2021). "Second, in vivo administration of IL-21 has the capacity to preserve intestinal Th17 cells and maintain mucosal barrier integrity in early SIV infection, limiting microbial translocation and systemic inflammation in the chronic phase of infection." (PMID 34491910, 2021). "In the current study, we tested the hypothesis that an in vivo immunomodulatory approach using IL-21 given at the time of immunization would augment the antibody response to flu vaccination in an aging and SIV-infection/ART-treated NHP model." (PMID 34491910, 2021). "Looking at the cytokine levels, there was observed up regulation of pro-inflammatory TNF-α induced proteins (TNFAIP6 [log2FC 2.6], TNFAIP8 [log2FC 5.3]) involved in systemic inflammation; and also, elevation of interleukins IL21 (Log2FC 3.7) and IL1 receptor (Log2FC 2.0) that respond to infection." (PMID 32000760, 2020). "These IFN-γ+IL-21+ hybrid Th1/Tfh cells are reminiscent of CD4 T cells identified in other persistent infections, leading us to investigate the role of continuing infection in their generation, and to identify molecular mechanisms regulating their generation." (PMID 32634740, 2020). "chabaudi‐specific IgM responses are not altered in the absence of IL‐21 signaling, thus showing that IgM is not sufficient to clear the infection, and that IL‐21 is essential to generate long‐lasting class‐switched protective B cell responses." (PMID 31733075, 2020). "Studies in a TH2-biased murine model of infection with H. polygyrus further confirmed that the two main cytokines secreted by TFH cells, IL-21 and IL-4, can cross-regulate the expression of T-bet and CD11c in the absence of an intact IFN-γ/IFN-γR signaling axis." (PMID 31867283, 2019).
infection (continued). "The IFN-γ-expressing T effector cells generated following P. chabaudi were predominantly positive for CXCR5, a marker for TFH cells, and acquired the ability to express IL-21 and IFN-γ, later in the course of infection and in the memory phase of the immune response." (PMID 31867283, 2019). "Together, these data indicate that RSV modulates the IL-21/STAT3 pathway in human memory CD8 T cells, and this could be a mechanism to be further explored to improve the memory response against the infection." (PMID 31780735, 2019). "In agreement with the gene array data, PleC CD4+ T cells did not produce IL-21 during the active Th2 phase of infection (d 20 pi), but did produce IL-21 protein at d 60 pi, during the hypo-responsive phase of infection." (PMID 31815932, 2019). "To address the role played by the IL-21/IL-21R signaling axis in CD4+ T cells in host protection after C. rodentium infection, we assessed the bacterial burden, the infection kinetics and survival rates in conditional knockout mice with a CD4+ T cells-specific deletion of STAT3 activity." (PMID 30818341, 2019). "The efficacy of IL-21 and IFNγ in modulating CD8 TRM differentiation may vary based on the duration of infection and the cells in the surrounding tissue parenchyma." (PMID 31514273, 2019). "CXCR5intPD-1int TFH cells were the primary source of IL-21 expression early during the course of infection, whereas TFH cells with high expression of CXCR5 and PD-1 (CXCR5highPD-1high) also expressed IL-21 during the resolution phase of the infection." (PMID 31867283, 2019). "Our data additionally demonstrate that IL-21 is not highly expressed in Foxp3+TFR cells during LCMV Cl13 infection, further indicating that IL-10+IL-21+Tfh cells are distinct from the TFR lineage." (PMID 30487586, 2018). "On the other hand, the expression of IL-21, IL-22, and IL-23 did not change significantly depending on the stage of infection." (PMID 29698503, 2018). "To further assess whether early antigenic or inflammatory signals are responsible for the induction of IL-10+IL-21+Tfh cells during persistent infection, we transiently depleted CD4 T cells at the time of infection." (PMID 30487586, 2018). "Of note, we did not observe any significant difference between groups in the total number of effector CD4 T cells responding to LCMV Cl13 infection, nor in the proportion or total number of IL-21+ single-producing Tfh cells." (PMID 30487586, 2018). "Evidence supports IL-21 being involved in the transition from innate immune responses to specific T cell responses against antigens so it would not be surprising for a number of infections to lead to IL-21 elevation as these results would support." (PMID 28427414, 2017). "Our data therefore identify two distinct populations of long-lived cells that are derived early following infection, likely via different mechanisms: a spleen IgM memory population that requires both CD4 T cell help and IL-21, and the CD4 T cell-independent BM ASCs." (PMID 28575114, 2017). "To examine the association of circulating common γ-chain cytokines with TB disease or infection, we examined the systemic levels of IL-2, IL-7, IL-15, and IL-21 in individuals with PTB, latent TB (LTB) or no TB infection (NTB)." (PMID 28448542, 2017). "IL-21 transcript levels were induced 10-fold in CD4+ T cells following infection; in contrast, little or no transcript was detected in CD8+ T cells." (PMID 27819295, 2016). "Consistent with impaired infection, levels of HIV-1 p24 protein were significantly reduced in supernatants from IL-21-treated HLACs compared with untreated controls, indicating that HIV-1 replication and overall viral production from infected cells were suppressed by IL-21." (PMID 26108174, 2015). "Because infected Il21-/- and Il21r-/- mice cannot make P. chabaudi-specific IgG responses, and in particular MBC responses, we reasoned that lack of IL-21 signaling would render these mice unable to control a re-infection." (PMID 25763578, 2015).